CXCL6 (C-X-C motif chemokine ligand 6)
Diseases named in the same sentence as CXCL6 in open-access papers (continued):
Sharing a sentence is not in itself a finding about the gene and the disease.
tumor (continued). "In our work, we identified that the expression of CXCL6 in HNSCC tissues was significantly upregulated when compared with non-tumor tissue." (PMID 33489879, 2020). "CXCL6 can be secreted from a variety of tumor cells, including OS cells, and plays crucial roles in the development of tumors." (PMID 30984000, 2019). "In particular, the neutralization antibody of CXCL6 attenuated the chemotaxis of neutrophils and inhibited tumour growth and metastasis in mouse model." (PMID 31147602, 2019). "In the present study, we measured in tumor tissue the quantity of the angiogenic chemokines CXCL6 and CXCL8 (IL-8) and the most widely studied angiogenic factor VEGF along with the angiostatic chemokine CXCL4." (PMID 29850390, 2018). "We found significantly increased levels of CXCL6 in tumor samples compared with those in the adjacent normal tissue." (PMID 29850390, 2018). "CXCL6, also known as GCP-2, is another pro-angiogenic cytokine with tumor growth promoting properties, and anti-CXCL6 antibodies reduced tumor growth and metastasis formation in vivo." (PMID 28951988, 2017). "Cancer cells facilitate recruitment of tumor-associated neutrophils (TANs) by expressing various of chemokines and cytokines, including CXCL5, CXCL6, and CXCL839, along with ligands that recognize receptors such as CXCR2 expressed by TANs40." (PMID 28223716, 2017). "Neutrophil recruitment can also be targeted by blocking CXCL8 or CXCL6 signaling with antibodies, and this approach has produced similar benefits in inhibiting tumor growth and metastasis." (PMID 26997761, 2016). "MMP7 and MMP9 induced syndecan 1 and CXCL6 production in tumor cells, which act as chemoattractants for neutrophils and mediate their influx to the tumor microenvironment." (PMID 26956475, 2016). "To explore the possible effects of CEACAM1 in tumor cells to neutrophils, we detected the mRNA expression of IL-8, CXCL-6 and MCP-1 in different CEACAM1 transfection groups." (PMID 24587171, 2014). "Overexpression of CEACAM1 on tumor cells correlated with more neutrophils infiltration to some extent through upregulating mRNA expression of IL-8 and CXCL-6." (PMID 24587171, 2014). "While the p38 MAPK signaling can regulate the production of a series of cytokines in the tumor microenvironment, including CXCL-6 and IL-8." (PMID 24587171, 2014). "Different C-C motif ligand-chemokines (CCL) and C-X-C motif ligand chemokines (CXCL), such as CCL2, CCL7, CXCL1 and CXCL6, are also potent stimulators of pro-malignant features, such as tumor cell proliferation, migration and invasion, as well as angiogenesis." (PMID 24887580, 2014). "Like CXCL8 and other members of the ELR+ CXC chemokine family, CXCL6 is a neutrophil chemoattractant that was recently demonstrated to promote tumor growth through its angiogenic effects in human tumors and animal models." (PMID 18578857, 2008). "CXCR2 chemokine ligands CXCL1, CXCL5 and CXCL6 were shown to be involved in chemoattraction, inflammatory responses, tumor growth and angiogenesis." (PMID 18578857, 2008). "Tumor profiling for CXCL6 is performed using a public database." (PMID 40305734, 2025). "Mapping the tumor microenvironment at a spatial resolution of 25 μm, MOMA revealed that CXCL6+ tumor cells recruited M2 macrophages through activation of the hepatocellular JAK-STAT3 pathway, which led to the formation of a spatially specific mechanism of the immunosuppressive microenvironment." (PMID 40697666, 2025). "Additionally, research by Wu’s team indicated that CXCL6, produced by highly invasive tumor cells, stimulates the release of SAA from damaged hepatocytes, encouraging macrophage infiltration and polarization via FPR1 and TLR2 receptors." (PMID 39457484, 2024). "Moreover, the tumor cell-derived CXCL6, CXCL2, and CCL20, TAM-derived CXCL9/CXCL10, and the stromal cell-derived CXCL12 also contributed to the accumulation of tissue-resident CD103+CD8+TILs in the TME." (PMID 37024870, 2023).
tumor (continued). "The biological role of CXCL6 in CC is to promote tumor growth, metastasis, and aggressiveness." (PMID 37893029, 2023). "By silencing CXCL6 and inhibiting miR-101-5p, the tumor cells had decreased colony formation and invasion compared to inhibiting miR-101-5p expression alone, suggesting CXCL6 is a direct target of miR-101-5p, and the CSC-like activity is reliant on CXCL6 expression." (PMID 36831112, 2023). "Few articles explored the association between tumor-derived CXCL5, CXCL6 and TAMs." (PMID 37865750, 2023). "Additionally, microRNA (miRNA) that is involved in E2F1 dysregulation exhibits a critical role in tumor progression, and CXCL6 influences miRNA function in carcinogenesis." (PMID 36835352, 2023). "In addition, we also constructed hypoxic cell models in Herp3B and Huh7 cells to verify the expression of genes in the prognostic model and found that C7, CLEC1B, and CXCL6 were not only related to the tumor stemness but also related to hypoxia." (PMID 36307751, 2022). "CXCL6 secreted by HCC cells can increase the HCC stemness and accelerate the progression of HCC by activating the extracellular signal-regulated kinase (ERK) 1/2 signaling pathway of tumor-associated fibroblasts (CAFs)." (PMID 36307751, 2022). "In addition, CCL2 was found to cooperate with CXCL6 to chemoattract neutrophils, accompanied by inflammatory cells infiltration in tumor sites." (PMID 36612163, 2022). "However, several cytokines have been shown to promote tumor growth through increasing angiogenesis, including CXCL6 and IL8." (PMID 32560387, 2020). "The results suggested that overexpression of CXCL6 contributed to tumor growth and pulmonary metastasis via activating PI3K/AKT and Wnt/β-catenin pathways, which could be repressed by treatment with CXCR2 antagonist SB225002." (PMID 30984000, 2019). "CXCL6 contributed to the recruitment of neutrophils within the tumour microenvironment." (PMID 31147602, 2019). "Inflammatory CC (CCL2, CCL3, CCL5) and CXC (CXCL1, CXCL2, CXCL5, CXCL6, and CXCL8) chemokines recruit at the tumor site CCR2+ monocytes and CXCR2+ neutrophils that differentiate into tumor associated macrophages (TAMs) and tumor associated neutrophils (TANs), exerting pro- or anti-tumoral role." (PMID 30894861, 2019). "Finally, overexpression of CXCL6 significantly contributed to tumor growth, pulmonary metastasis and activation of PI3K/AKT and β-catenin pathways in nude mice in vivo, which were repressed by treatment with CXCR2 antagonist." (PMID 30984000, 2019). "CXCR1 has also been involved in tumor metastasis, as it binds CXCL6 and CXCL8." (PMID 30591657, 2018). "The overexpressed CEACAM1 may attract more neutrophils to tumor sites through up-regulating IL-8 and CXCL-6 expression." (PMID 24587171, 2014). "However, in recent years a number of studies have emerged demonstrating CXCL6 involvement in tumor development and angiogenesis in various animal models and human tumors." (PMID 18578857, 2008). "Additionally, the CXCL6 secreted by the tumor cell cluster could induce damage to hepatocytes (SAAs+ hepatocytes) via activation of the JAK-STAT3 pathway." (PMID 37337030, 2023). "Moreover, the p-AKT/AKT ratio and nuclear β-catenin level in tumor tissues were enhanced in CXCL6-overexpressed group, whereas administration of SB225002 could reverse these changes." (PMID 30984000, 2019). "Moreover, CXCL6 production by endothelial cells within gastrointestinal tumors was shown to contribute to tumor development and neovascularization and constitutive CXCL6 secretion was recently demonstrated in a panel of small cell lung cancer (SCLC) cell lines and in clinical SCLC specimens." (PMID 18578857, 2008). "The directional movement of PMN-MDSCs is modulated by the release of C-X-C motif chemokines from tumor cells, including CXCL1, CXCL5, CXCL6, CXCL8, and CXCL12." (PMID 40722739, 2025).
tumor (continued). "Upregulated pro-inflammatory chemokines CXCL6 and CXCL5, along with ECM-degrading enzymes MMP1 and MMP13, create a feedback loop that sustains inflammation and facilitates tumor-supportive immune infiltration." (PMID 40604111, 2025). "IL-17A can selectively elevate the expression of chemokines with angiogenic properties by epithelial cells as well as tumor cells, such as CXCL1, CXCL5, CXCL6, and CXCL8." (PMID 38515019, 2024). "Within the 250 μm wide region adjacent to the tumour border, the damaged area induces high expression of SAA1 and SAA2 by CXCL6." (PMID 39350478, 2024). "RT-qPCR results showed that tumor tissues exhibited significantly higher expression levels of CXCL3 and CXCL6 mRNAs compared with matched normal tissues, which were in line with the results from the UALCAN database." (PMID 37161430, 2023). "In these patients, high expression of CXCL6 and CXCR2 closely correlated with tumor infiltration by M2 macrophages, disease progression, and poor prognosis." (PMID 37509721, 2023). "Neutrophils are recruited to tumors mainly by ELR+-CXC chemokines produced by tumor cells (e.g., CXCL8, CXCL5, and CXCL6) and by neutrophils themselves (e.g., CXCL2) or by other cells of the tumor stroma." (PMID 35158948, 2022). "While the comparison of expression data between tumor and normal samples showed that 8 out of 36 ARGs were significantly differentially expressed, including CCND2, CXCL6, KCNJ8, LPL, SERPINA5, SLCO2A1, VTN, and APOH." (PMID 35836112, 2022). "CAFs secrete cardiotrophin-like cytokine factor 1 (CLCF1) inducing the production of CXCL6 and transforming growth factor-β (TGF-β) by tumor cells deriving TANs polarization into N2 phenotype and promoting tumor stemness." (PMID 36613878, 2022). "A recent study showed that CAF-derived cardiotrophin-like cytokine factor 1 (CLCF1) induces TAN-N2 polarization by increasing the expression of CXCL6 and TGF-β in tumor cells, thereby accelerating tumor progression." (PMID 35784290, 2022). "We then performed a trans‐well migration assay with active CXCL6 or DPP4‐truncated CXCL6 in the lower chamber and neutrophils isolated from the tumor‐bearing mouse in the top chamber." (PMID 34378358, 2021). "The M-MDSC is attracted to tumor sites by CCL2, CCL5, and CSF1 and PMN-MDSC was attracted by CXCL1, CXCL5, CXCL6, CXCL8, and CXCL12." (PMID 34858479, 2021). "In HCC-TME, CAF-derived cardioctonutrient-like cytokine 1(CLCF1) increases the secretion of CXCL6 and TGF-β in tumor cells, thereby promoting tumor stem cell growth." (PMID 34869376, 2021). "Similar findings were obtained when analyzing the expressions of CXCL6 and CXCL8 in tumor or non‐tumor tissues." (PMID 34185422, 2021). "CXCL16 is the ligand of CXCL6, and CXCR6 upregulation is critical for continuous tumor control mediated by CD8+ cytotoxic T cells." (PMID 35127816, 2021). "It has been shown that certain tumours produce chemotactic agents, such as TNFα; IL‐17; CXCR2 ligands CXCL1, CXCL2, CXCL5, and CXCL6, to attract neutrophils." (PMID 33665979, 2021). "Specifically, CLCF1 released by CAFs induced the production of CXCL6 and TGF-β by tumor cells, which acted on tumor cells themselves, promoting their stemness, and on TANs, driving their N2 polarization." (PMID 34200529, 2021). "The highest upregulation in LECs after direct interaction with the tumor cells was observed for the cytokines CCL7 and CXCL6." (PMID 31963450, 2020). "IL-17 induces the secretion of CCL2, CXCL1, CXCL5, CXCL6, and CXCL8 from several types of cells that infiltrate the tumor, and subsequently, it recruits myeloid-derived suppressor cells, including tumor-associated macrophages." (PMID 32756356, 2020). "Among the chemokine ligands, CXCL1, CXCL2, CXCL6, and CXCL9 genes also displayed a higher expression in tumors with BD3 compared to low-grade tumor budding." (PMID 32719800, 2020).
tumor (continued). "The chemokines CXCL1, CXCL2, CXCL5, CXCL6, and CXCL8 secreted from tumor cells attract neutrophils in the blood to the tumor microenvironment via CXCR1 and CXCR2 on the surface of neutrophils." (PMID 30736371, 2019). "Neutrophils are recruited at the tumor sites by several chemokine signals, such as CXCL12, CXCL8, CCL3 (MIP-1α), and CXCL6 (huGCP-2), or murine chemokines CXCL1, CXCL2, and CXCL5." (PMID 30591657, 2018). "CXCL6, also named granulocyte chemotactic protein-2 (CXCL6/GCP-2), is another chemokine involved in the regulation of tumor angiogenesis." (PMID 30591657, 2018). "We detected a concentration gradient for the CXCR2 ligands CXCL1, CXCL2, CXCL5, CXCL6 and CXCL8 between the plasma and the tumor tissues of patients with primary RCC." (PMID 28923105, 2017). "In tumor cells, its activation is altered and it drives the production of pro-angiogenic cytokines, including CXCL1 and CXCL6." (PMID 28951988, 2017). "The CXCL1, CXCL5, and CXCL6 chemokines have the ELR motif proximal to the CXC sequence, and all ELR containing CXC chemokines have been shown to be potent promoters of tumor hemangiogenesis." (PMID 28624797, 2017). "CXCL6 and CXCL8 play significant roles in tumor progression and inflammatory responses." (PMID 40696350, 2025). "CXCL6 functions through the CXCR1/2‐JAK‐STAT/PI3K axis and reshaping tumor lipid metabolism." (PMID 40305734, 2025). "Furthermore, CAFs have been reported in hepatocellular carcinoma to recruit neutrophils by secreting SDF-1α and induce the polarization of N2 phenotype neutrophils by upregulating CXCL6 and TGF-β expression in tumor cells, thereby promoting tumor progression." (PMID 40890855, 2025). "Differential tumor expression was further confirmed by IHC staining of the “Surgery cohort” tissue microarray (TMA) from Zhongshan Hospital, allowing us to reach the same conclusion that CXCL6 is overexpressed in tumor tissue (P < 0.001)." (PMID 40305734, 2025). "While chronic inflammation promotes tumor progression, tumor cells themselves also attract immune cells via chemokines such as IL-8, CCL2 (MCP-1), CCL3 (MIP-1α), CCL5 (RANTES), CXCL6 (huGCP-2), and cytokines such as IL-1β, IL-6, TNFα, GM-CSF, and G-CSF, inducing inflammation." (PMID 36614196, 2023). "Three of them (CXCL10, CXCL6 and CXCL16) belong to the chemokine (C‐X‐C motif) ligand (CXCL) family, which are known to play key roles in inflammatory diseases, neoplastic transformation and tumour growth regulation." (PMID 36608258, 2023). "Other evidence suggests that CXCL6 and APOH are potent oncoproteins that promote tumor growth." (PMID 37161430, 2023). "If we could examine the downstream effect of CXCR1 compared to CXCR2 when bound to CXCL8 or CXCL6, we could evaluate which downstream pathways elicit pro-CSC-like characteristics in the tumor cells." (PMID 36831112, 2023). "The rest genes, CD46, CXCL6, GPI, ITGB1, PLA2G6 and TNFSF4, were revealed for the negative association with tumor suppression." (PMID 35832540, 2022). "Using in vitro co-cultures of breast and prostate cancer cells with lymphatic endothelial cells (LEC), Oliveira-Ferrer demonstrated tumor-dependent induction of C3, CFB and C1q secretion as well as that chemokine upregulation (CCL7, CXCL6, CXCL1) by the LECs promotes tumor metastasis." (PMID 35860237, 2022). "Furthermore, N2, or protumorigenic polarization of neutrophils within the tumor can be induced through CAF-derived cardiotrophin-like cytokine factor 1 (CLCF1), which upregulates CXCL6 and TGF-β on tumor cells." (PMID 36010899, 2022). "We hypothesized that CXCL6, S100A2, and SDC1 lead to tumor progression and immune escape by raising gamma delta T cells and reducing CD8+T cells, but this hypothesis needs further verification." (PMID 35432485, 2022). "Furthermore, various neutrophil-attracting chemokines (CXCL1, CXCL2, CXCL5, CXCL6, and CXCL8) promote the migration of neutrophils to the tumor site through CXCR1 and CXCR2 receptors." (PMID 36091114, 2022).
tumor (continued). "These suggest that CXCL6 may promote the progression of HCC by simultaneously affecting the stemness and oxygenation status of tumor cells." (PMID 36307751, 2022). "Meanwhile, we found that the concentrations of CXCL6 and CXCL8 in tumor tissue culture supernatants (TTCS) or tumor tissues were obviously augmented in contrast with those in non‐tumor tissue culture supernatants (NTCS) or non‐tumor tissues." (PMID 34185422, 2021). "As a recent study of hepatocellular carcinoma reported, CAF-derived cardiotrophin-like cytokine factor 1 (CLCF1) induces the polarization of N2-phenotype neutrophils by upregulating CXCL6 and TGF-β expression in tumor cells, thereby facilitating tumor progression." (PMID 34635121, 2021). "So, in this study, SB225002, as a CXCR2 antagonist, may also block the effect of CXCL6, CXCL8 on the communication between OS cells and tumor microenvironment, which needs to be evaluated in our future research." (PMID 30984000, 2019). "However, there was a significant difference for CXCL6 (p = 0.005) and VEGF (p = 0.003) between tumor and normal tissue." (PMID 29850390, 2018). "Furthermore, CXCL6, CXCL7 and CXCR2 were down‐regulated in Gal‐3‐knockdown tumour spheres, while CXCR2 overexpression in Gal‐3‐knockdown RCC restored the ability of sphere formation." (PMID 30246456, 2018). "Tumor upregulated chemokines included the followings: CXCL5 (138 fold increase); CCL25 (70 fold increase); CXCL11 (26 fold increase); CXCL6 (20 fold increase); CXCL1 and CXCL10 (11 fold increase); CXCL3 (8 fold increase); and CXCL9, CXCL2, and CCL3L1 (6 fold increase)." (PMID 29088818, 2017). "Whilst CXCL6 exhibited a strictly FB-type-specific induction profile regardless of the invasiveness of the tumor cell line, CSF2 was only induced in co-cultures of invasive cell lines regardless of the partnered FB type." (PMID 25919140, 2015). "It was inferred from microarray analyses of tumour cell-MSC co-cultures that several cytokines may be expressed in the tumour cells that act to promote these effects: CXCL1, CXCL5 and CXCL6, IL-6 and IL-8." (PMID 21902837, 2011). "In contrast to CXCL6, we demonstrated CXCL1 and CXCL5 mRNA and protein expression to be significantly up-regulated in CRC and CRLM tissue specimens in relation to their matched tumor neighbor tissues." (PMID 18578857, 2008). "In conclusion, VEGF-A, MMP-10, and CXCL6 share features of non-functional, anti-inflammatory tumor-promoting markers that may be induced upon selected stimuli." (PMID 31824496, 2019). "Interestingly, the previously reported tumor angiogenesis gene HMGB1 displays parallel actions to BRD7 knockdown as it induces the expression of different pro-angiogenic cytokines, including IL8, CXCL1 and CXCL6." (PMID 28951988, 2017). "Moreover, HCC-stimulated MSCs could enhance the recruitment of other cells to the tumor milieu, probably through the secretion of chemokines such as CXCL8/IL-8, CXCL1-2-3/GRO and CXCL6/GCP-2." (PMID 29113298, 2017). "Finally, upon tumor fibroblast interaction the massive induction of chemokines such as CXCL1 and CXCL6 in FBs might be responsible for increased recruitment of a monocytic cell line (THP-1) in a transwell assay." (PMID 25919140, 2015). "Furthermore, we detected a significant clinicopathological association between CXCL5 expression and early tumor categories of CRC (P < 0.001), which did not occur for CXCL1 or CXCL6." (PMID 18578857, 2008).